LTBR (lymphotoxin beta receptor)
Diseases named in the same sentence as LTBR in open-access papers (continued):
Sharing a sentence is not in itself a finding about the gene and the disease.
tumor (continued). "Importantly, this group established the role of LIGHT-LTβR signaling in tumor clearance by showing that an anti-LTβR antibody prevented therapeutic functioning of MSC-LIGHT, directly implicating LIGHT-LTβR interactions." (PMID 32499782, 2020). "The DNA methylation and expression levels of PHYHD1, LTBR, MYBPHL, C22orf42, PRR5, ANKDD1A, RAB13, CAMKV, KIFC3, WNT4 and STAT6 are associated with tumor invasion, and these genes may become the potential genes for targeted therapy." (PMID 31796052, 2019). "In addition, it seems that LTβR signaling plays context-dependent roles, exerting either tumor-suppressive or promoting functions in solid tumors." (PMID 31137630, 2019). "By activating LTβR in stroma cell, this treatment up-regulates the expression of various cytokine and chemokine in tumor microenvironment, resulting in the increased T-cell infiltration and T cell-inflamed tumor microenvironment." (PMID 31281318, 2019). "We speculate the LTβR-mediated enhancement of proliferation is augmenting progression and skewing the pathological appearance of AKT/CAT-associated tumour phenotypes, such as ICC-like lesions." (PMID 26206664, 2016). "Whether HEV development and growth are driven by dendritic cells and/or LTβR signaling in tumor blood vessel EC in clinical cancer remains to be determined." (PMID 26155419, 2015). "LTβR dependent HEV neogenesis in seen in experimental animals in which LT-α or LIGHT are directly targeted to tumor cells, raising the possibility that cells other than dendritic cells could drive HEV neogenesis in cancer." (PMID 26155419, 2015). "Interestingly, though the tumor cells utilized for these studies expressed high levels of surface LTβR, we were unable to induce cell death through this receptor pathway." (PMID 22389673, 2012). "We wanted to determine if tumor cell irradiation alone could enhance LTβR mediated cell death signaling in a manner similar to that observed with Fas and TRAIL killing, in the absence of exogenous cytokines." (PMID 22389673, 2012). "Under these conditions, tumor cell irradiation was not able to increase the susceptibility to cell death induced by LTβR signaling, and cell death remained below 3% in all cell lines." (PMID 22389673, 2012). "It remains to be determined, however, if irradiation could further enhance cell death of tumor cells treated with anti-LTβR mAb and IFN-γ in combination and this is currently under investigation." (PMID 22389673, 2012). "Meanwhile, knockout of LTBR in TAMs could prolong the survival of tumor‐bearing mice." (PMID 39429877, 2024). "Hence, LTβR signaling induces tumor cell death in a reactive oxygen species (ROS) dependent way, limits the capacity of tumor cells recruiting immune suppressor cells, assists the extravasation of leukocyte to acting locus, regulates immune cell migration, and maintains splenic microenvironments." (PMID 35057080, 2022). "In this context, TNFR in addition to LTβR signaling may prove crucial for tumor-associated TLS formation as opposed to primarily LTβR driven processes as seen during peripheral LN development." (PMID 34122434, 2021). "Additionally, neo-antigen load correlated with increased expression of the chemokines TNFRSF25, CCR1, and LTBR, which may serve as valuable targets in future tumor immunology studies." (PMID 29487705, 2018). "Interestingly, the treatment of immunotherapy-resistant Ag104Ld tumors with Ab-LIGHT (homologous to lymphotoxin)-based therapy can activate the lymphotoxin β receptor (LTβR) signaling specifically in tumor cells which is leading to enhanced secretion of multiple chemokines." (PMID 30631358, 2018). "Moreover, prolonged administration of LTβR-Fc significantly reduced mean serum levels of the cotransfected oncogene reporter Gaussia luciferase by threefold confirming a reduction in tumour burden." (PMID 26206664, 2016).
tumor (continued). "LTβR signalling is well known to recruit lymphoid and myeloid cells into lymphoid organs and tumours, and activation mediates accumulation of macrophages and NKT/T cells in association with increased expression of CXCL10 and CCL2 in AKT/CAT and AKT/NICD tumours." (PMID 26206664, 2016). "We found that TGFB1/EGFR, LTA/LTBR, CD46/JAG1, and AREG/EGFR ligand‐receptor pairs were stronger in CD4+ T cell‐Plac1+ tumor cells than in CD4+ T cell‐Plac1− tumor cells, among which LTA/LTBR expression was highly specific for Tregs and Plac1+ cells." (PMID 40056047, 2025). "Tregs secrete lymphotoxin beta (LTB), engaging with lymphotoxin beta receptor (LTBR) on MCs and influencing tumor progression." (PMID 41035074, 2025). "Reports have shown that LTβR agonists induce TA-HEV formation and enhance lymphocyte infiltration in various mouse tumor models." (PMID 41331976, 2025). "In a glioblastoma model, the combined treatment of LTβR agonists, VEGFR2 inhibitors, and PD-L1 inhibitors produced a significant anti-tumor response." (PMID 41331976, 2025). "In CT26 colon cancer mice, an agonistic anti-murine LTβR monoclonal antibody ACH6 increased the infiltration of T cells and B cells, inhibiting tumor growth." (PMID 39198425, 2024). "For example, strong interactions existed between the tumor cells and B cells, CD4+ T cells, CD8+ T cells or Tregs through the lymphotoxin and lymphotoxin beta receptor (LTB-LTBR)." (PMID 38191598, 2024). "The immune checkpoint TNFSF14 in Neutrophils, NK Cells, and Monocytes and BTLA in Treg Cells, Granulosa Cells, and B Cells interact with LTBR and TNFRSF14 in Cancer Cells to mediate cytotoxicity and promote tumor killing." (PMID 36401283, 2022). "In the same GBM tumor model, LIGHT-VTP treatment in combination with anti-VEGF and anti-PD-L1 is even more effective than agonistic LTβR antibodies, and generates an abundance of intratumoral HEV+ TLS and granzyme B+ (GrzB) CD8+ effector T cells." (PMID 34122434, 2021). "Lastly, delivery of LTBR+ stroma demonstrates functional TLS formation when injected subcutaneously juxtaposed to established MC-38 murine colon carcinoma tumors, slowing tumor growth and actively priming T cell response." (PMID 34054863, 2021). "Studies have shown that PD-1 mAb and anti-VEGFR2 agent combination treatment could promote tumor vessel normalization and induce high endothelial venules (HEVs), which promoted lymphocyte infiltration and activity through the activation of lymphotoxin β receptor (LTβR) signaling." (PMID 33680942, 2020). "Particularly notable in that study was the enhanced production of IL-6, IL-8 and CXCL1 in the tumor lines resistant to anti-VEGF treatment, the same cytokines that were upregulated in stromal cells upon LTβR stimulation in our study." (PMID 29983872, 2018). "Constructed with a scFv:LTβR fused to the N- or the C-terminus of the heavy chain of TRA-8 antibody, both BsAbs inhibited tumor growth of LTβR-expressing cells in vivo." (PMID 31548531, 2017). "We observed that the mRNA expression of CCL5 and CCR5 as well as LTβR-related chemokines, such as CCL21, CCL19 and CXCL13 were substantially enhanced in the tumor tissue of EL4-Axl-bearing mice compared with mock control." (PMID 28423548, 2017). "Day 90 histological evaluation of tumour nodules supports direct collaboration between AKT and LTβR signalling, averaging 11.4 (Ig, n=7) vs 29.4 (anti-LTβR, n=7) nodules/liver following 8 weeks of treatment." (PMID 26206664, 2016). "The activation of LTβR by LTα1β2 (a cell-bound heterotrimeric complex of LTα and LTβ) and LIGHT promotes tumor growth in an NF-κB-dependent manner." (PMID 25369740, 2015). "LTβR agonism has been shown to promote TLS formation and immune activation, whereas antagonistic strategies such as ligand traps may suppress tumor-supportive LTβR signaling in immunosuppressive compartments." (PMID 41716391, 2026).
tumor (continued). "In addition, the expression of receptors, including TNFSF14, CD40, LTBR, and VTCN1, was elevated in LN-out tumor cells." (PMID 38519500, 2024). "Therefore, high expression of HOIP in tumor cells is likely translated into high LUBAC activity, even more so if this correlates with enhanced LTβR expression." (PMID 39215104, 2024). "Subsequent in-vivo experiments revealed that LTβR agonist significantly increased the number of TA-HEVs per tumour area in RT2-PNET tumours but not in MMTV-PyMT tumours." (PMID 37287625, 2023). "LTβR agonist treatment increased the frequency and numbers of TA-HECs in both WT and Rag2−/− mice suggesting the direct activation of LTβR on tumour endothelial cells irrespective of the presence of immune cells." (PMID 37287625, 2023). "Corresponding to this finding, we found no increase in tumor-infiltrating lymphocyte number as a result of administering LTβR agonist Abs despite the presence of HEV." (PMID 36704666, 2022). "Although imaging methods clearly revealed that HEV were induced by LTβR agonist Abs even when Treg were present, we found that this did not result in control of tumor growth." (PMID 36704666, 2022). "While administration of LTβR agonist Abs combined with Treg depletion resulted in development of HEV networks in all tumors, this was accompanied by only a very modest improvement in tumor control and T-cell infiltration." (PMID 36704666, 2022). "Herein, we further show that induction of HEV in the absence of Treg depletion (induced by LTβR agonist Abs) does not promote T-cell infiltration and control of tumor growth." (PMID 36704666, 2022). "Similarly, the selective targeting of LIGHT [a ligand that signals through LTβR and herpes virus entry mediator (HVEM)] to tumour vasculature via vascular targeting peptides (VTPs) also results in vessel normalisation and HEV induction." (PMID 33132107, 2021). "However, administration of a LTβR agonist, together with anti-PD-L1 and anti-VEGF/VEGFR, led to the induction of HEVs and a reduced tumour burden." (PMID 33132107, 2021). "Moreover, prolonged LTβR activation significantly enhanced proliferation, skewing AKT/CAT-induced tumour morphology towards the appearance of ICC-like lesions and accelerating AKT/NICD-initiated ICC." (PMID 26206664, 2016). "In a similar manner, induced expression or ectopic delivery of LTβR downstream mediators, CCL19 or CCL21, in the TME results in inhibition of tumor growth or complete rejection of established tumors associated with increased infiltration by CD3+CCR7+ T cells and/or DCs in a range of cancer models." (PMID 24348473, 2013). "However, the role of LTβR in CD4+ T cell differentiation and tumor immunity is unclear." (PMID 40436857, 2025). "Based on these findings, we administered STING agonist ADU-S100 (cGAMP analog) and LTβR agonistic antibody (4H8) to tumor-bearing mice to examine whether activation of STING and LTβR pathways will induce TLS formation in TLS-free tumors by reproducing the microenvironment of TLS-rich tumors." (PMID 40897896, 2025). "Similarly, LTβR agonists and LIGHT induced HEV and TLS formation, increased lymphocyte filtration, and enhanced the anti-tumor effects of ICI, prolonging the survival period of tumor-bearing mice." (PMID 41029827, 2025). "Three weeks after inoculation, tumor weight analysis showed that no matter clodronate liposome treatment or knockout of LTBR in macrophages partially hindered tumor progression, but the combination strategy showed no additive effects, indicating the critical role of LTBR+ TAMs in LLC progression." (PMID 39429877, 2024). "In the subsequent analysis of the potential pathways between GrB+ B cells and tumor cells, the most important incoming and outgoing L-R pairs were the signaling complexes, macrophage migration inhibitory factor (MIF) -(CD74 + CXCR4) and lymphotoxin-alpha (LTA)–(LTB + LTBR), respectively." (PMID 38386050, 2024).
tumor (continued). "Interestingly, in both tumour models blockade of LTβR signalling did not abrogate PNAd expression or the extent of immune infiltration." (PMID 37287625, 2023). "However, despite clear increases in the extent of TA-HEVs, LTβR agonist-treated tumours did not have significantly more TILs or better control of tumour growth." (PMID 37287625, 2023). "Importantly, only when LTβR agonist treatment was combined with dual ICB were there significant increases in CD8+ tumour infiltrating lymphocytes (TILs) which were accompanied by improved responses to therapy and tumour regression." (PMID 37287625, 2023). "Importantly, by tracking the fate of labelled ECs following the cessation of CTLA4 blockade + LTβR agonist treatment, TA-HEVs were found to promptly transition back to a PCV state concomitant with a significant diminishment in CD3+ aggregates and tumour relapse." (PMID 37287625, 2023). "LTβR expression in the lungs correlated with inflammation, at least in COPD; therefore, increased LTβR expression in tumors may enhance inflammation and promote tumor growth." (PMID 33917839, 2021). "LTβR-accelerated tumour burden was further documented by increased levels of the transfected oncogenes NICD, with increased levels of AKT, activated pAKTThr308, pAKTSer473, NICD and Hes1 observed at day 40 by western blot with liver lysates derived from AKT/NICD/anti-LTβR treated mice." (PMID 26206664, 2016). "In addition, a number of studies have reported that LTβR is involved in tumor angiogenesis, most likely through the non-canonical NF-κB pathway." (PMID 25369740, 2015). "There are no reports on the impact of radiation on tumor cell expressed LTβR." (PMID 22389673, 2012). "Similarly, IFN-γ has been reported to enhance LTβR-induced cell death in tumor cells treated with the mAb (31G4D8) but was not essential for LTβR death induced by a pentameric form of the antibody (CBE11)." (PMID 22389673, 2012). "Moreover, tumor cell irradiation did not sensitize cells to LTβR-induced cell death, as it did for Fas and TRAIL-induced death." (PMID 22389673, 2012). "Additionally, it would be interesting to see if radiation can enhance tumor cell death triggered by the pentameric LTβR (which is not commercially available)." (PMID 22389673, 2012). "Expression levels of interleukin-13 (IL-13), leptin, lymphotoxin β receptor (LTbR), and macrophage inflammatory protein 1β (MTP1β) were significantly higher and expression level of IL-11Rα was lower for tumor-positive nodes as compared with tumor-negative SN." (PMID 24212647, 2011). "However, the role of LTβR in CD4+ T cell differentiation and anti-tumor activity remains unclear." (PMID 40436857, 2025). "Indeed, examination of dense PNAd+ clusters at 2× magnification confirmed that the addition of LTβR agonist drives the formation of a densely packed HEV network which contrasts with the largely well-separated PNAd+ vessels seen in the Treg-depleted tumor without LTβR agonist." (PMID 36704666, 2022). "In the PyMT tumour model, LTα1β2 lymphotoxin production by CD8 T cells and NK cells were shown to drive TA-HEV formation via signalling through the LTβR/noncanonical NFkβ axis." (PMID 37287625, 2023). "The strategies above highlight the critical role of LTβR-activated non-canonical NF-κB pathway in TLO formation and functions in anti-tumor immunity." (PMID 31281318, 2019). "Not surprisingly, we observed no tumor cell death in SW620, HCT116, or WiDr cells following treatment with the LTβR mAb alone." (PMID 22389673, 2012). "Whether continued LTβR treatment in the absence of immune activation following treatment cessation of CTLA4 blockade + LTβR agonist is sufficient to maintain TA-HEVs and their lymphocyte aggregates which drive control of tumour growth was not determined in this work." (PMID 37287625, 2023).
cancer (50 papers, 2009 to 2025). A tumor composed of atypical neoplastic, often pleomorphic cells that invade other tissues. "While the role of LTβR as a receptor is well-documented, recent studies have linked high LTβR expression with poor prognosis in various cancers, suggesting its critical role in key cellular processes." (PMID 40883295, 2025). "To uncover cancer-associated pathways associated with LTBR expression, we utilized Gene Ontology (GO), Kyoto Encyclopedia of Genes and Genomes (KEGG), and gene set enrichment analysis (GSEA)." (PMID 38175686, 2024). "Due to its association with immunity, LTBR and its ligands have gained attention as promising targets for the treatment of immune diseases and cancers." (PMID 38175686, 2024). "The intracellular signaling patterns associated with the anti-cancer effects of treating HeLa cells with recombinant LTBR protein will be investigated in future studies." (PMID 35563525, 2022). "Moreover, elevated LTβR expression in several cancer types has been associated with poor patient prognosis." (PMID 40883295, 2025). "As we previously showed that LUBAC acts as a gatekeeper for cell death induction by TNF, FasL and TRAIL, independently of NF-κB regulation, we next examined whether LUBAC deficiency could sensitize cancer cells to death induced by LTβR activation." (PMID 39215104, 2024). "LTBR is significantly overexpressed in most cancers and is associated with low patient survival." (PMID 38175686, 2024). "Notably, LTBR expression has been linked to the expression of five MMR genes in human pan-cancer, particularly THCA, PGPC, and LIHC." (PMID 38175686, 2024). "Interestingly, Cluster 2 showed that upregulations of CD117/c-kit and LTBR signaling have been implicated in lymphoid tissue development and tertiary lymphoid structures during development and in cancer." (PMID 36230839, 2022). "In addition, for both GSEA and cancer-related functions at the single-cell level status, we found that LTBR exhibited associations with various processes in different cancers, including angiogenesis, apoptosis, DNA damage, DNA repair, cellular hypoxia, and inflammogenesis." (PMID 38175686, 2024). "The thymus of mice with cancer cachexia exhibited degradation of the thymic medulla and decreased expression of LtβR, Mmp9 and Ccl19 in thymus medullary fibroblasts (mFbs)." (PMID 40665793, 2025). "Since STING agonists are clinically available and humanized agonistic monoclonal antibodies to LTβR can be developed, this strategy is readily translatable to clinical use for cancer treatment." (PMID 40897896, 2025). "Despite its known role in inducing apoptosis, the reason for LTβR overexpression in certain cancers remains poorly understood." (PMID 40883295, 2025). "In comparison, mice treated with the LTβR agonist monoclonal antibody or in combination with the STING agonist induced numerous TLS that resembled human cancer TLS composed of dense clusters of B cells surrounded by CD3+ T cells and HEV vessels." (PMID 40897896, 2025). "Gene Ontology (GO), Kyoto Encyclopedia of Genes and Genomes (KEGG), and Gene Set Enrichment Analysis (GSEA) were used to explore the role of LTBR in pan-cancer." (PMID 38175686, 2024). "Lymphotoxins produced by cancer cells activate the LTBR-NF-κB signaling pathway in stromal fibroblasts, leading to the expression of chemokines." (PMID 38175686, 2024). "Using Western blotting, we corroborated that LUBAC is recruited to the LTβR-SC in a LIGHT-stimulation-dependent manner in four different cancer cell lines." (PMID 39215104, 2024). "The results of the study showed that LTBR was expressed at a higher level in cancer cell lines compared to normal cell line." (PMID 39068665, 2024). "In summary, we investigated the biological functions and prognostic relevance of LTBR in diverse cancers." (PMID 38175686, 2024).